EDN1 (endothelin 1)
Diseases named in the same sentence as EDN1 in open-access papers (continued):
Sharing a sentence is not in itself a finding about the gene and the disease.
ischemic stroke (54 papers, 2005 to 2025). A stroke disorder caused by obstruction of blood flow to the brain, due to thrombotic (local blood clot formation) or embolic (due to a blood clot or other material traveling from another site) event. "Astrocytes are also capable of producing endothelin-1, and the astrocyte-derived endothelin-1 is increased when mice are subjected to ischemic stroke caused by transient middle cerebral artery occlusion, resulting in progressive neurodegeneration." (PMID 39122454, 2024). "This meta‐analysis was designed to determine an accurate estimate of the association between the EDN1 Lys198Asn SNP and the risk of ischemic stroke." (PMID 31566901, 2019). "The present meta‐analysis suggests that Lys198Asn polymorphism of EDN1 gene is associated with an increased risk for ischemic stroke." (PMID 31566901, 2019). "Our meta‐analysis suggests a significant association of Lys198Asn polymorphism of EDN1 gene with ischemic stroke." (PMID 31566901, 2019). "Plasma levels of endothelin-1 are elevated in ischemic stroke and are associated with cerebral edema." (PMID 31058815, 2019). "A subgroup analysis based on ethnicity revealed that the Lys198Asn polymorphism of the EDN1 gene was associated with ischemic stroke only in Caucasians." (PMID 31566901, 2019). "We therefore conducted a meta‐analysis to investigate the association between Lys198Asn polymorphism of EDN1 gene and susceptibility of ischemic stroke." (PMID 31566901, 2019). "Another study showed that genetic polymorphisms of the EDN1 rs5370 T allele and rs2070699 G allele were associated with an increased risk of ischemic stroke, which is contrary to our findings." (PMID 28882114, 2017). "Meta‐analysis established a significant association between Lys198Asn SNP of EDN1 gene and ischemic stroke when assuming either recessive model (OR: 1.30; 95% CI: 1.02–1.65; p = .03; I2 = 41%) or dominant model (OR: 1.48; 95% CI: 1.24–1.76; p < .001; I2 = 61%)." (PMID 31566901, 2019). "Meta‐regression analysis was used to explore whether the methodological quality scores of the included studies play an important role in the association between the Lys198Asn polymorphism of the EDN1 gene and the risk of ischemic stroke." (PMID 31566901, 2019). "Our meta‐analysis suggests a significant association of Lys198Asn SNP of EDN1 with ischemic stroke." (PMID 31566901, 2019). "Meta‐analysis established a significant association between Lys198Asn polymorphism of EDN1 gene and ischemic stroke when assuming either recessive model of inheritance (OR: 1.30; 95% CI: 1.02–1.65; p = .03; I2 = 41%) or dominant model of inheritance (OR: 1.48; 95% CI: 1.24–1.76; p < .001; I2 = 61%)." (PMID 31566901, 2019). "Among the top globally prevalent neurological conditions is ischaemic stroke, endothelin-1 being frequently involved in its pathophysiology." (PMID 41153763, 2025). "We induced focal demyelination by lysolecithin (LPC) injection and ischemic stroke by endothelin 1 (ET1) injection into the internal capsule." (PMID 40221393, 2025). "Ischemic stroke was induced after 30 min of baseline recording by injection of endothelin-1 onto the cortex adjacent to the micro-electrode array." (PMID 38793822, 2024). "Other reports show an increased ipsilateral GFAP density after endothelin-1-induced ischemic stroke." (PMID 38674304, 2024). "Long-term cortical atrophy and WM changes were observed in an endothelin-1 model of ischaemic stroke and contralateral WM changes in regions connected to the initial infarction site provide evidence of SND." (PMID 35898722, 2022). "The potent vasoconstrictor peptide, Endothelin-1 (ET-1), has previously been utilised in animal models to reduce local blood flow to levels that mimic ischemic stroke." (PMID 33947043, 2021). "NBP has been shown to promote remyelination and increase the integrity of white matter after endothelin-1-induced focal permanent ischemic stroke in rats." (PMID 32038259, 2019).
ischemic stroke (continued). "Rats were subjected to ischemic stroke while they were conscious by infusing endothelin-1 (Et-1) through a guide cannula that was implemented in the vicinity of the middle cerebral artery (MCA)." (PMID 31920629, 2019). "There are several works that concern the investigation of the effect of EDN1, EDNRA, and EDNRB genetic polymorphisms on ischemic stroke (IS) development." (PMID 29849817, 2018). "Intracortical microinjections of endothelin-1 (ET-1) were delivered to the motor cortex of Long Evans rats to induce ischemic stroke, with animals sacrificed 6 weeks later." (PMID 28261086, 2017). "Ischemic stroke model was induced by stereotaxic intracerebral injection of vasoconstricting agent endothelin-1 (ET-1)." (PMID 24324296, 2013). "In this study we investigate the role of NADPH oxidase in brain angiogenesis after transient endothelin-1 (ET-1) induced ischemic stroke in rats." (PMID 24961316, 2013). "Similar changes in microglia/macrophages and SK3 immunoreactivity were seen after an ischemic stroke was induced by injecting endothelin-1 into the striatum." (PMID 20074365, 2010). "Another one protein (EDN1) has an effect on ischemic stroke." (PMID 32690984, 2020). "Thus, we conducted a meta‐analysis to investigate the association between Lys198Asn polymorphism of ET‐1 gene (EDN1) and risk of ischemic stroke." (PMID 31566901, 2019). "Under ischemic stroke conditions, endothelin-1 (ET-1) is upregulated in astrocytes." (PMID 31733648, 2019). "However, in dominant model, the Lys198Asn SNP of the EDN1 gene was associated with ischemic stroke in Caucasians but not in Asians." (PMID 31566901, 2019). "Furthermore, Lys198Asn SNP can also be coinherited together with another gene highly associated with ischemic stroke due to physical proximity or with a highly functional SNP within the EDN1 gene itself, for the same reasons as above, and can structurally alter ET‐1." (PMID 31566901, 2019). "The aim of this 3-year follow-up prospective study was to evaluate suPAR levels in patients with a first ischemic stroke in correlation with CRP, PCT, NT-proCNP and endothelin 1-21 and to investigate the impact of suPAR on the outcome." (PMID 35053782, 2021). "Edn1 is regulated by Hif1-α and the lack of this anti-survival factor in Hif1-α deficient mice might protect from early acute neuronal cell death and neurological impairment in the very acute phase after ischemic stroke." (PMID 31660990, 2019). "Serum endothelin-1 levels are elevated in ischemic stroke and ICH, and endothelin-1 serum levels correlate with ICH hematoma volumes." (PMID 30836997, 2019). "Studies of ischemic stroke have also previously been performed in pigs using the photothrombotic model, mechanical MCA occlusion models, and intracortical injection of endothelin-1 (ET-1)." (PMID 38793822, 2024). "At the same time, Zhang and Sui did not reveal an association between EDN1 rs5370 and EDNRA rs5335 polymorphic sites with ischemic stroke development among women of the Chinese Han population." (PMID 29849817, 2018). "Thus, the administered combination of the angiotensin AT1 blocker Candesartan and the endothelin-1 ETA blocker ZD1611 systemically resulted in reduced infarct size and in a better neurological score after ischemic stroke in rat but not in enhanced receptor expression induced by MCAO." (PMID 20187933, 2010).
prostate carcinoma (53 papers, 2000 to 2025). A carcinoma that arises from epithelial cells of the prostate gland. "Metastatic prostate cancer cells produce increased amounts of endothelin-1 which causes sustained osteoblast differentiation." (PMID 29867053, 2018). "In recent years, several biomarkers associated with prostate cancer were examined such as endothelin-1." (PMID 29515640, 2017). "Endothelin-1 (ET-1) inhibits osteoblast differentiation, melatonin inhibits prostate cancer bone metastasis by inhibiting ET-1, making melatonin a promising therapy." (PMID 40756978, 2025). "Conversely, osteoblastic metastasis in prostate cancer results from excessive bone formation activated by many factors such as endothelin-1 (ET-1), BMPs, PDGF, and TGF-β." (PMID 35994202, 2022). "Previous in vitro studies have shown that FOXA1 increases pro-angiogenic factors, including EGF, endothelin-1, and endoglin in prostate cancer cells and promotes endothelial cell proliferation, migration, and tube formation." (PMID 35627227, 2022). "Other studies also reported the effect of EDN1 towards cell metastasis in hepatocellular, gastric and prostate cancer 38,39,40." (PMID 33995625, 2021). "Prostate cancer cells secrete factors, such as bone morphogenic proteins (BMPs), TGFβ, and endothelin-1 (ET-1), which increase osteoblastic activity and lead to osteoblastic metastases." (PMID 32722128, 2020). "As for prostate cancer bone metastasis, EDN1 secreted by cancer cells can bind to EDNAR expressed on osteoblasts, leading to osteoblast proliferation and thereby an increase in bone density." (PMID 31753020, 2019). "Endothelin-1 (ET-1) is known to have a role in the pathogenesis of cancer, particularly prostate cancer." (PMID 31137764, 2019). "Prostate cancer cells express endothelin-1 (ET-1) that binds its receptor (ETR) on the osteoblasts, stimulating Wnt signaling." (PMID 29642618, 2018). "ECE-1c is involved in endothelin-1 synthesis, which also participates in invasion in vivo in breast, ovary, and prostate cancer cells." (PMID 28134850, 2017). "They showed that human prostate cancer cell line produces endothelin-1 messenger RNA and secretes immunoreactive endothelin-1." (PMID 29515640, 2017). "They selected 14 patients with confined prostate cancers and 16 patients with metastatic cancer and found endothelin-1 positivity in 87% of patients." (PMID 29515640, 2017). "Prostate cancer cells growing at bone express endothelin-1 (ET-1) that stimulates osteoblasts via the endothelin A receptor (ETR), activating Wnt signaling." (PMID 27618899, 2016). "Endothelin-converting enzyme-1c (ECE-1c) is a membrane metalloprotease involved in endothelin-1 synthesis, which has been shown in vitro to have a role in breast, ovary and prostate cancer cell invasion." (PMID 26543229, 2015). "Most prominent in recent publications is the endothelin axis, with reports linking endothelin-1 to prostate cancer tumorigenesis." (PMID 22809218, 2012). "Endothelin-1 can also synergise the proliferative effects of other peptide growth factors in various prostate cancer cell lines." (PMID 15083188, 2004). "Clinical and preclinical data have indicated a mitogenic role for small regulatory peptides such as endothelin-1 (ET-1), bradykinin, bombesin-like peptides and neurotensin in various stages of prostate cancer." (PMID 15083188, 2004). "Co-culture of human prostate cancer cell lines with bone slices was determined to increase the level of endothelin-1 (ET-1) mRNA and its production." (PMID 10917552, 2000). "Furthermore, small regulatory peptides such as endothelin-1 exert mitogenic effects on prostate cancer progression through binding to the endothelin A receptor that results in the modulation of various kinases involved in cellular signalling." (PMID 35158943, 2022).
prostate carcinoma (continued). "Prostate cancer expressing endothelin 1 (ET-1) was shown to preferentially metastasize to the bone because ET-1 binds to the endothelin receptor A (ETA) on bone marrow stromal cells and, therefore, causes proliferation and activation of bone-forming osteoblasts." (PMID 34064589, 2021). "Endothelin-1 (ET-1) and the ETA receptor have been implicated in prostate cancer progression." (PMID 34067832, 2021). "Our finding was consistent with a previous study on prostate cancer, which revealed that EDN1 might modulate bone metastases from prostate cancer." (PMID 33995625, 2021). "In addition, osteoblast stimulation and the secretion of endothelin-1 (ET-1) by prostate cancer cells have been demonstrated to suppress Dickkopf-1 (DKK-1), which stimulates Wingless-related integration site (Wnt) signaling and osteoblast bone deposition." (PMID 32640686, 2020). "Accordingly, EDN1 seems to be a potential therapeutic target of metastatic prostate cancer, and blocking the EDN1-EDNAR signaling pathway could potentially inhibit the progression of bone metastasis." (PMID 31753020, 2019). "Furthermore, secretion of endothelin-1 by prostate cancer cells has been demonstrated to suppress DKK1, stimulating Wnt signaling and osteoblast bone deposition." (PMID 29867053, 2018). "Adjusting the baseline variables of PSA and PN, the Endothelin-1 positivity could effectively predict EPE in patients with prostatic cancer (OR: 6.04, p= 0.010)." (PMID 29515640, 2017). "Increases in PSA may lead to greater production of endothelin-1, a protein that stimulates osteoblasts and inhibits osteoclasts in the presence of androgen-insensitive prostate cancer cells." (PMID 21826255, 2011). "For example, prostate cancer cells secrete BMPs, TGF-β, IGF-1, PDGF, endothelin-1 (ET-1), VEGF and micro-RNA (miR)-940, which promote osteoblast differentiation and activation." (PMID 34831167, 2021). "In prostate cancer a similar mechanism with involvement of prostate specific antigen (PSA) and endothelin-1 (ET-1) has been described." (PMID 29644008, 2018). "Endothelin 1 (ET-1) and its receptors ETA and ETB have an important role to play in the biology of prostate cancer, especially the osteoblastic response of bone to metastasis." (PMID 19675766, 2007). "Prostate cancers secrete a variety of factors, such as BMP and endothelin-1 (ET-1), which promote the maturation of osteogenic precursor cells, PTHrP, which inhibits osteoblast apoptosis, aminoproteinases, which indirectly promote bone formation, and urinary fibrinogen activator (uPA)." (PMID 38464516, 2024). "Prostate cancer cells secrete BMP1, IGF, PDGF, vascular endothelial growth factor (VEGF), endothelin 1 (EDN1), plasminogen activator urokinase (PLAU) and kallikrein-related peptidase 3 (KLK3; also known as PSA), which regulate osteoblast proliferation or differentiation." (PMID 31753020, 2019). "Bone metastatic prostate cancer cells secrete factors that promote osteoblast differentiation, including bone morphogenic proteins (BMPs), TGF-beta, IGF-1, platelet-derived growth factor, endothelin-1, and VEGF." (PMID 29867053, 2018). "Endothelin-1-induced contractions were similar in strength to noradrenaline-induced contractions in laser-enucleated tissues, and to endothelin-1-induced contractions in tissues from prostate cancer patients without prior surgery for BPH." (PMID 40519781, 2025). "In prostate tissues from patients undergoing surgery for prostate cancer (PCa) and without prior surgery for BPH, endothelin-1 and thromboxane A2 induce full contractions, potentially maintaining increased smooth muscle tone and symptoms even despite α1-blocker treatment." (PMID 40519781, 2025).
pulmonary fibrosis (50 papers, 2007 to 2025). Chronic progressive interstitial lung disorder characterized by the replacement of the lung tissue by connective tissue, leading to progressive dyspnea, respiratory failure, or right heart failure. "Increased expression of ECE1 and its target endothelin-1 (Et-1) has previously been implicated in studies in pulmonary fibrosis in rat models and in human idiopathic pulmonary fibrosis and correlated with disease activity." (PMID 39363014, 2024). "EDN1 has been implicated in pulmonary fibrosis and TNF-induced EndMT in cardiac fibrosis." (PMID 37841308, 2023). "Additionally, EDN1 drives fibroblast activation, proliferation, and differentiation into myofibroblasts, leading to excessive collagen deposition, a potential risk factor for the development of pulmonary fibrosis." (PMID 40002743, 2025). "Endothelin-1 (ET-1) is a potent vasoactive peptide that plays a multifaceted role in the pathogenesis of lung fibrosis via promoting fibroblast activation and inflammation." (PMID 40897757, 2025). "Piezo1 is activated in response to cyclic pressure and drives c-JUN activation, endothelin-1 overexpression and HIF1α stabilization, facilitating the pro-inflammatory program in mouse lung fibrosis." (PMID 38267432, 2024). "In pulmonary fibrosis, many of these signaling pathways are also activated by vasoactive peptide endothelin-1 (ET1) and lysophosphatidic acid." (PMID 37047710, 2023). "Intraperitoneal injection of 50 mg/kg crocetin reduced skin and lung fibrosis in bleomycin-induced scleroderma mice, mainly owing to the reduction of endothelin-1 (ET-1)." (PMID 35095483, 2021). "Thus, a potential candidate gene found within this region is EDN1 (endothelin-1), a vasoconstrictor associated with several cardiovascular diseases and inflammatory and fibrotic processes, acting as fibroblast mitogen in systemic sclerosis, pulmonary fibrosis, and hepatic fibrosis." (PMID 31636655, 2019). "Fibroblasts express no or only low levels of the CTGF, however, it is overexpressed during wound repair by fibrotic mediators such as TGF-β, thrombin, and endothelin-1 (ET-1) that contribute to the pulmonary fibrosis." (PMID 25121739, 2014). "In patients with SSc-ILD, the expression of EDN1 is increased in lung tissues, and the blockade of EDN1 could be an effective method to limit the progression of lung fibrosis." (PMID 34222222, 2021). "Numerous cytokines have been implicated in the pathogenesis of lung fibrosis, including transforming growth factor-β (TGF-β), tumour necrosis factor-α (TNF-α), platelet- derived growth factor (PDGF), insulin-like growth factor-1 (IGF-1), endothelin-1 (ET-1) and the interleukins, (IL)-1 and IL-8." (PMID 28974751, 2017). "Furthermore, we also found that LPS‐induced expressions of extracellular matrix genes such as TNC and HYAL1, as well as a vasopressor gene, EDN1, all of which are involved in the process of lung fibrosis, were also dose dependently downregulated by antofine treatment." (PMID 28805975, 2017). "Recently, diagnostic biomarkers such as endothelin-1 and procollagen type III amino terminal propeptide have been shown to be elevated in pulmonary fibrosis but further studies are necessary to consolidate the approval of use of such biomarkers for the diagnosis of pulmonary fibrosis." (PMID 23618386, 2013). "In addition, the activated platelets and endothelial cells could secrete profibrotic mediators, inducing tumor growth factor 1 (TGF-1), serotonin, endothelin-1 (ET-1), and vesicles, which would further amplify the endothelial damage, lung fibrosis, and evolution of SSc into PH." (PMID 40141024, 2025). "It was reported that TNFα-induced endothelin-1 (ET-1) upregulates GM-CSF production from airway smooth muscle cells (ASMCs) and that GM-CSF was increased in the bronchoalveolar lavage fluid (BALF) of patients with pulmonary fibrosis." (PMID 25838639, 2015).
pulmonary fibrosis (continued). "Endothelin-1 blockade has been shown to block TGF-β-induced myofibroblastic differentiation in cultured lung fibroblasts, and an ET-1 antagonist has been shown to delay death in a cohort of idiopathic pulmonary fibrosis patients." (PMID 24758615, 2014). "In particular, microRNA regulation of genes of hepatocyte growth factor-, endothelin-1- or IGF1- signaling, and specific molecular mechanisms of cancer, may affect lung fibrosis." (PMID 23987664, 2013). "Endothelin-1 has also been suggested as a biomarker in patients with interstitial lung disease, independent of the condition’s form (idiopathic pulmonary fibrosis, where ET-1 plays a profibrotic role, or interstitial lung disease associated with autoimmune diseases)." (PMID 41153763, 2025).